IL6 (interleukin 6)
Diseases named in the same sentence as IL6 in open-access papers (continued):
Sharing a sentence is not in itself a finding about the gene and the disease.
Hyperglycemia (continued). "First, hyperglycemia-induced oxidative stress leads to excessive reactive oxygen species production and activation of the NF-κB signaling cascade, promoting secretion of IL-6, TNF-α, and MCP-1, which further recruit neutrophils and perpetuate kidney inflammation." (PMID 41492002, 2026). "Our findings demonstrate that hepatic IL-6/STAT3 signaling also contributes to maintaining metabolic homeostasis in the face of an intestinal microbiome that can induce mature-onset body fat accumulation and hyperglycemia when IL-6 trans-signaling is inhibited." (PMID 41362820, 2026). "During hyperglycemia, ROS also stimulates VSMCs to release IL-1, Interleukin 6 (IL-6), Interleukin 1 beta (IL-1β), TNFα, histamine, and bradykinin, which disrupt the junctions between endothelial cells, increase permeability, and thereby facilitate the passage of monocytes and oxLDL." (PMID 40362167, 2025). "The connection between hyperglycemia and heightened IL-6 levels may amplify the inflammatory response, contributing to more severe symptoms." (PMID 40026986, 2025). "In stratified analyses, in non-diabetic AMI patients stress hyperglycemia at admission was independently associated with the cytokines IL-6, IL-8, IL-10, CCL20, and MCP-1." (PMID 39962379, 2025). "Mechanistically, exercise increases muscle glucose uptake and insulin sensitivity ‒ limiting chronic hyperglycemia and the formation of damaging advanced glycation end‐products ‒ while also stimulating the release of myokines (e.g., irisin, IL‐6) that exert anti‐inflammatory and anabolic effects." (PMID 40915183, 2025). "Hypertriglyceridemia and hyperglycemia, which are key components of the TyG index, activate macrophages and promote the release of pro-inflammatory cytokines such as interleukin-6 (IL-6) and tumor necrosis factor-alpha (TNF-α), driving chronic low-grade systemic inflammation." (PMID 40421215, 2025). "In that analysis, IL-6 correlated positively with time below range but negatively with time above range (TAR), suggesting that hypoglycemia may be a stronger acute driver of IL-6 release than hyperglycemia." (PMID 41010714, 2025). "Sleep disturbances and insomnia can increase inflammatory cytokines (hs-CRP, tumor necrosis factor, interleukin 6) and enhance the hypothalamic-pituitary-adrenal activity, leading to reduced β-cell function, increased insulin resistance, and contributing to hyperglycemia." (PMID 41114778, 2025). "Additionally, advanced glycosylation products, which are by-products of hyperglycemia, and even glucose itself, can increase the production of inflammatory cytokines like IL-6 and CRP." (PMID 40951890, 2025). "Elevated levels of cortisol and inflammatory biomarkers such as C-reactive protein (CRP) and interleukin-6 (IL-6), common to both conditions, may contribute to both hyperglycemia and depressive symptoms." (PMID 40726880, 2025). "Moreover, when subjected to hyperglycemia, the flow‐based co‐culture more than doubles the IL‐6 and insulin secretions compared to their monoculture levels and continued to rise under days of extended exposures." (PMID 40746010, 2025). "Existing hyperglycaemia during GDM, due to insulin insufficiency, is known to cause certain immune dysfunction that leads to leukocyte dysfunction and the increased production and secretion of cytokines, like IL-1β, IL-6 and TNF-α." (PMID 39518962, 2024). "IL-6 is in the pro-inflammatory cytokine family and a major player in the human cytokine network, hence variations in its levels should be explored when studying the relationship between hyperglycemia and lung microbiota in TB pathogenesis." (PMID 39981106, 2024). "In our systematic review, it was mentioned that probiotics could prevent hyperglycemia by reducing the levels of IL-6 and TNF-α, thereby improving insulin sensitivity." (PMID 38529045, 2024). "Increased inflammatory activity,as measured by elevated levels of IL-6 and TNF-, may be linked to hyperglycemia, as measured by HbA1c." (PMID 39132231, 2024).
Hyperglycemia (continued). "Moreover, hyperglycemia induces the production of numerous inflammatory factors, such as IL-6 and TNF-α, that can induce epithelial mesenchymal transition, thereby promoting tumor cell invasion and inhibiting apoptosis." (PMID 38152132, 2023). "Due to postprandial hyperglycemia and hyperlipidemia, there is an increase in circulating pro-inflammatory cytokines (IL-1β, TNFα and IL-6) in the blood, which originate from adipose tissue and connective tissue cells and promote chronic low-grade inflammation." (PMID 38137918, 2023). "In fact, it has been reported that pro-inflammatory cytokines (e.g., TNFα, interleukin 1β (IL-1β), interleukin 18 (IL-18) and IL-6) are increased in acute hyperglycemia, whereas in the opposite condition, when insulin is working, these cytokines are significantly decreased." (PMID 38137918, 2023). "Therefore, hyperglycemia stimulates T cells and T cell-derived products, including IL-1, IL-6, IL-17, and IL-22, which are of central importance in progressive fibrosis in DKD." (PMID 36776877, 2023). "Additionally, in vitro studies in a first trimester trophoblast cell line have demonstrated that hyperglycemia induces the secretion of diverse inflammatory cytokines, including interleukin (IL) -1β, IL-6 and IL-8." (PMID 36982317, 2023). "Interestingly, both TNF-α and IL-6 have been shown to increase similarly during experimental hyperglycemia along with rises in IL-18 and FGF-21 and suppression of VEGF." (PMID 37400734, 2023). "In addition, we found that the protein expression of IL-6 downregulated distinctly both in the renal cortex and medulla during hyperglycemia." (PMID 37467292, 2023). "Several studies have found that LPS or other factors, such as polymeric immunoglobulin A1 (pIgA1) and hyperglycemia, can activate mesangial cells to produce pro-inflammatory cytokines, including IL-6, transforming growth factor-beta 1 (TGF-beta 1), TNF-α and NO." (PMID 37488573, 2023). "It was also shown that patients who had hyperglycaemia also had elevated IL-6 and D-dimer levels." (PMID 36895058, 2023). "The pro-inflammatory environment resulting from hyperglycemia and/or insulin resistance is the result of the higher expression of inflammatory mediators, such as IL-1β, IL-6, TNF-α, TGF-β, IKKβ, and JNK, that may have local or systemic action." (PMID 36552014, 2022). "We showed that hyperglycemia enhanced the proinflammatory response of M(IFNγ) to Hb-Hp complex uptake by stimulating the production of TNFα, IL-1β, IL-6, IL-8, and IL-1RA, supporting the observation that hyperglycemia itself can induce the secretion of proinflammatory cytokines." (PMID 35163309, 2022). "Several studies have shown that curcumin improves insulin sensitivity, decreases hyperglycemia, improves insulin levels, reduces proinflammatory mediators such as interleukin (IL-6, IL-1β) and tumor necrosis factor-α (TNF-α) in diabetic patients, and increases their global antioxidant power." (PMID 36297570, 2022). "Recovery from hypoglycemia has also been implicated in inflammatory mechanisms, with IL‐6 levels elevated in hyperglycemia but not normoglycemia following hypoglycemia in patients with T1D and healthy individuals." (PMID 36250653, 2022). "Additionally, our results showed that BA treatment significantly ameliorated hyperglycemia-mediated NFκB p65 transcriptional activation, subsequently decreasing the release of pro-inflammatory cytokines, including IL1β, IL6 and MCP1." (PMID 35415192, 2022). "Furthermore, in human monocytes, hyperglycemia induces decreases in the histone repressor mark H3K9me3 at IL-6 promoter, accompanied by increased IL-6 expression and exacerbation of inflammation." (PMID 35883538, 2022). "TFP5 treatment decreased hyperglycemia-induced IL-6, IL-1β, and TNF-α upregulation." (PMID 35874807, 2022).
Hyperglycemia (continued). "Besides, a case study from Chile revealed that low concentrations of urine Ni (median of 1.88 μg/L, with 25% of subjects’ urine concentrations above 2.55 μg/L) with hyperglycemia and elevated levels of the inflammatory mediator IL-6 were interrelated." (PMID 35682008, 2022). "Inducing hyperglycaemia in rats significantly increased the levels of serum glucose, haemoglobin A1c, total cholesterol, triglycerides, high-density lipoprotein, interleukin 6, tumour necrosis factor alpha, amyloid β 42, total plasma tau, and neurofilament light." (PMID 35802659, 2022). "Several studies focused on risk factors associated with poor prognosis, including elder age, comorbidities, lymphopenia, D-dimer greater than 1 μg/L, elevated CRP, high LDH, high hypersensitive troponin I, high interleukin-6, hyperglycemia, and hypoproteinemia." (PMID 33413721, 2022). "Therefore, hyperglycemia through these pathways activates proinflammatory cytokines such as interleukin 1, interleukin 6, and finally, nuclear factor kappa-light-chain-enhancer of activated B cells (NF-KB), which play a central role in inflammation." (PMID 35497930, 2022). "Additionally, hyperglycemia raises IL-6 levels in the blood, presumably due to elevated production in monocytes." (PMID 35959169, 2022). "In addition, systemic inflammation and increased proinflammatory cytokines (e.g., tumor necrosis factor-α, interleukin-1, and interleukin-6) can lead to impaired insulin signaling, thereby exacerbating hyperglycemia." (PMID 34206813, 2021). "In DME, chronic hyperglycemia generates metabolic changes resulting in an increase in inflammatory cyto- and chemokines such as interleukin 6 (IL-6), IL-8, TNFα, or ICAM-1 which might alter vascular permeability and disrupt the blood-ocular barrier." (PMID 34884622, 2021). "Hyperglycaemia in type II DM has a direct effect on the development of inflammatory conditions induced by the increased expression of proinflammatory cytokines such as interleukin‐6 (IL‐6)." (PMID 34277984, 2021). "Besides, hyperglycemia also induces the production of IL-6 from endothelium and macrophages, thus generating a vicious cycle." (PMID 33547367, 2021). "Some biomarkers previously demonstrated to be associated with hyperglycemia during critical illness (IL-6, sTNFr1) were not strongly associated with average glucose or risk of hyperglycemia in our study." (PMID 33755703, 2021). "Other prognostic factors associated with disease progression include increased levels of interleukin-6, hypoalbuminemia, hyperglycemia, thrombocytopenia, lymphopenia, leukocytosis, high ratio of a number of neutrophils to a number of lymphocytes, and liver or kidney impairment." (PMID 34804705, 2021). "As indicated by the further test of pro-inflammatory genes, the hyperglycemia-induced overexpression of IL-6 and MCP-1 in renal tissues of diabetic mice could be effectively downregulated by ISL treatment (10 or 20 mg/kg)." (PMID 33288747, 2020). "Persistent hyperglycemia triggers expression of various proinflammatory cytokines and chemokines, including interleukin-6 (IL-6), interleukin-8 (IL-8), interleukin-1α (IL-1α), and tumor necrosis factor-alpha (TNF-α, which in turn leads to an increase in the inflammatory response." (PMID 33147748, 2020). "Therefore, unchecked IL-6/STAT3/SOCS3 signaling driven by cancer-derived metabolic waste directly impairs insulin signaling to promote hyperglycemia." (PMID 32193527, 2020). "Furthermore, hyperglycemia has been shown to damage immune function, especially the innate immune system, and increase inflammatory cytokines, such as interleukin-6." (PMID 33381599, 2020). "Interestingly, in the T2D patients under treatment (but still with hyperglycemia) we observed increased levels of ICAM-1, VCAM-1 and IL-8 in PBMCs associated to ROCK activation whereas their circulating of both IL-6 and IL-8 were similar to controls." (PMID 32375786, 2020).
Hyperglycemia (continued). "Hyperglycemia may trigger inflammatory process elevating proinflammatory cytokines, IL-6 and TNF-α, expression, possibly due to ROS production or reduction of antioxidant defense systems." (PMID 31998774, 2020). "Moreover, both doses of Physalis fruits extract decreased IL-6 levels and increased IL-10 in hyperglycemia in parallel with a reduction of caspase-3." (PMID 32824505, 2020). "Furthermore, STZ-induced hyperglycemia increased the expression of Tnf-α and Il-6 mRNA in the hippocampus of diabetic mice, whereas the expression levels of these cytokines were significantly attenuated in the Lcn2-deficient mice." (PMID 30761088, 2019). "Previous study has implicated astragaloside could improve vascular endothelial dysfunction induced by hyperglycemia by increasing eNOS expression and decreasing the content of IL-6." (PMID 31619994, 2019). "The mechanism for this finding, with respect to interleukin-6, may due to hyperglycaemia in the higher GI group, which induces the release of inflammatory cytokines from monocytes." (PMID 31336986, 2019). "Interestingly, cells cultivated in normoxia and hyperglycemia exhibited an increased expression of IL-6 after 17 hours compared to that after 1 hour." (PMID 31415598, 2019). "In particular, iatrogenic hyperglycemia can lead to impaired wound healing, neuronal dysfunction, increased production of the inflammatory cytokines interleukin-6 (IL-6) and tumor necrosis factor-α (TNF-α), inhibition of leukocyte function, vasculitis, and ultimately a poorer clinical outcome." (PMID 31998762, 2019). "Besides increasing the oxidative stress level, hyperglycemia also increases proinflammatory cytokine levels, such as interleukin-6 and tumor necrosis factor (TNF)-α." (PMID 31514311, 2019). "Moreover, in vitro hyperglycemia induced TLR-4 expression via PKC leading to increased levels of IL-6 and chemokine (CC motif) chemokine ligand 2 (CCL-2), via IkB/NF-kB pathway." (PMID 31835864, 2019). "A reduction in postprandial hyperglycemia may partly explain how yogurt inhibited postprandial IL-6 in obese women." (PMID 29767743, 2018). "So at beginning, we speculated that there might be a possible association between the phosphorylation site of STAT3 and the activation modes of IL‐6 signalling, which subsequently plays different roles in podocyte impairment during hyperglycaemia." (PMID 28881473, 2018). "Additionally, we found that the protection against olanzapine-induced hyperglycemia with prior exhaustive exercise was intact in whole body IL-6−/− mice or in mice that had been treated with an IL-6 neutralizing antibody." (PMID 29335597, 2018). "We hypothesized that exercise would blunt SGA-induced hyperglycemia through a mechanism involving IL-6." (PMID 29335597, 2018). "In this context of inflammation, hyperglycemia affects Tumor necrosis alpha (TNFα) and interleukin 6 (IL6) plasma levels, as well as local VEGF levels, while retinal hypoxia induce the release of cytokines, chemokines, and growth factors from macrophages and microglia." (PMID 29614818, 2018). "Thus, we are interested in exploring the role of IL‐6 classic and trans‐signalling in podocyte impairment during hyperglycaemia, especially their individual roles." (PMID 28881473, 2018). "Thus, it suggests that the axis of both IL‐6/IL‐6R and IL‐6/gp130 is harmful to podocyte under hyperglycaemia." (PMID 28881473, 2018). "In human, chronic subcutaneous administration of IL-6 induces hyperglycemia." (PMID 30584465, 2018). "In these patients, dsDNA has also been correlated with the IL-6 concentration, which may suggest a role for NETosis in the interactions between hyperglycemia and inflammation as well as in the consequences of inflammation." (PMID 28220120, 2017). "This condition might be due to the release of the early neuropoietic cytokines like TNF-α, IL-1β, and IL-6 at the interphase of hyperglycemia induced biochemical changes and nerve damage." (PMID 28381989, 2017).
Hyperglycemia (continued). "The aim of our study was to evaluate the effect of low-power laser irradiation at two wavelengths (635 and 830 nm) on the secretion of inflammatory factors (TNF-α and IL-6) by the endothelial cell culture—HUVEC line (human umbilical vein endothelial cells)—under conditions of hyperglycemia." (PMID 26861982, 2016). "Our results show the significant increase of IL-6 induced by hyperglycemia (P = 0.0002); LLLT did not cause significant changes in the concentration of this cytokine in the endothelial cell culture." (PMID 26861982, 2016). "This excessive production of IL-6 and TNF-α may also be a result of oxidative stress and inflammatory changes caused by hyperglycemia." (PMID 27379252, 2016). "We reported that serum levels of IL-1beta and IL-6 in diabetes-prone mice at an age before hyperglycemia developed were 2-3 times higher than for age-matched heterozygous control mice, suggesting that low-grade systemic inflammation develops early in the disease process." (PMID 27843953, 2016). "In studies using umbilical vein endothelial cells, fluctuant hyperglycemia could significantly increase the content of IL-6, TNF-α and ICAM-1 in vitro." (PMID 27496150, 2016). "The aim of our study was to evaluate the effect of low-power laser irradiation at two wavelengths (635 and 830 nm) on the secretion of inflammatory factors (TNF-α and IL-6) by the endothelial cell culture—HUVEC line (human umbilical vein endothelial cell)—under conditions of hyperglycemia." (PMID 26861982, 2016). "The result we have obtained may be in favor of beneficial effects of LLLT, since IL-6 reducing TNF-α level can therefore protect cells from the damaging effect of hyperglycemia." (PMID 26861982, 2016). "Our observation of reduced IL‐6 expression with hyperglycemia differs from previous publications." (PMID 27042306, 2016). "Hyperglycemia also causes enhanced cycle oxygenize-2 (COX-2) expression and prostaglandin E2 (PGE2) production, which induces IL-6 expression in tubular epithelial cells, contributing to the development of glomerulosclerosis, interstitial fibrosis, and albuminuria." (PMID 26770985, 2016). "However, in spite of an initial rise at 12 hrs time-point following hyperglycaemia (approximately 2.5-fold for both these transcripts), at 48 hrs the level of such up-regulations were lower (1.5- and 2-fold increase for IL-6 and TNF-α respectively)." (PMID 25787249, 2015). "Indeed, hyperglycemia stimulates expression of IL6 in trophoblasts and placental expression of IL6 and TNFA is increased, but their levels in the fetal circulation are unchanged or even reduced." (PMID 25258707, 2014). "Interestingly, hyperglycemia alone increased the expression of IL-6 (P < 0.05) and decreased the expression of IL-1β (P < 0.05), when compared to normal glycemia under inflammatory conditions." (PMID 24000330, 2013). "Hyperglycemia induced p38 mitogen-activated protein kinase activation, leading to increased infiltration of macrophages and increased levels of interleukin (IL)-1, IL-6 and tumor necrosis factor-α." (PMID 24499158, 2013). "Meanwhile, the changes of TNF-α might be better and earlier than those of IL-6 in predicating CAD during postchallenge hyperglycemia in patient with AbnGT." (PMID 22397368, 2012). "Additionally, humoral factors, including pro-inflammatory cytokines, such as tumor necrosis factor-alpha (TNF-α), interleukin-6 (IL-6), and interleukin-1 beta (IL-1β), further exacerbate hyperglycemia by impairing insulin signaling and increasing hepatic glucose output." (PMID 40868089, 2025). "We demonstrated that the microvascular morphological changes of pancreas are highly correlated with progressive inflammatory infiltration and proinflammatory cytokine production, including TNF-α, IL-1β, and IL-6, which could lead to β cell decline and hyperglycemia with age." (PMID 40066372, 2025).